AP3S1 (adaptor related protein complex 3 subunit sigma 1)
Description:
Part of the AP-3 complex, an adaptor-related complex which is not clathrin-associated. The complex is associated with the Golgi region as well as more peripheral structures. It facilitates the budding of vesicles from the Golgi membrane and may be directly involved in trafficking to lysosomes. In concert with the BLOC-1 complex, AP-3 is required to target cargos into vesicles assembled at cell bodies for delivery into neurites and nerve terminals.
Synonyms: CLAPS3; Sigma3A
Tractability: Small molecule: a structure with a bound ligand is known. Antibody: UniProt places it where antibodies can reach, with medium confidence. PROTAC: ubiquitination databases record sites on it; its protein half-life has been measured.
Gene: Protein-coding gene on chromosome 5 (115,841,422 to 115,914,086, forward strand). Ensembl gene ENSG00000177879.
Subcellular location: Golgi apparatus; Cytoplasmic vesicle membrane
Subcellular location (Human Protein Atlas): Vesicles
Pathways (Reactome):
Vesicle-mediated transport: Golgi Associated Vesicle Biogenesis
Gene Ontology:
Molecular function: protein binding; AP-3 adaptor complex binding
Biological process: anterograde axonal transport; anterograde synaptic vesicle transport; clathrin-coated vesicle cargo loading, AP-3-mediated; insulin receptor signaling pathway; melanosome assembly; platelet dense granule organization; synaptic vesicle coating; synaptic vesicle recycling; vesicle-mediated transport; Golgi to vacuole transport; intracellular protein transport; protein transport
Cellular component: AP-3 adaptor complex; AP-type membrane coat adaptor complex; early endosome; transport vesicle; axon cytoplasm; cytoplasmic vesicle membrane; Golgi apparatus; membrane; membrane coat; presynapse
Genetic constraint (gnomAD): Loss-of-function variants: 7 observed, 9.12 expected, observed/expected ratio (o/e) 0.77, 90% interval 0.44 to 1.43. That is too few expected variants to judge how well the gene tolerates losing a copy. Missense variants: 69 observed, 126.61 expected, observed/expected ratio (o/e) 0.54, 90% interval 0.45 to 0.67. Synonymous variants: 31 observed, 40.35 expected, observed/expected ratio (o/e) 0.77, 90% interval 0.58 to 1.04.
Homologues: Orthologues: chimpanzee AP3S1 (100% identical), dog AP3S1 (100% identical), guinea pig AP3S1 (100% identical), macaque AP3S1 (100% identical), mouse Ap3s1 (100% identical), tropical clawed frog ap3s1 (79% identical), Drosophila melanogaster or (75% identical), Caenorhabditis elegans aps-3 (73% identical). Paralogues in human: AP3S2 (84% identical), AP1S1 (31% identical), AP2S1 (31% identical), AP1S2 (31% identical), AP1S3 (30% identical), AP4S1 (30% identical).
Diseases named in the same sentence as AP3S1 in open-access papers:
AP3S1 is named in the same sentence as 17 diseases in open-access papers, as found by Europe PMC text mining. Sharing a sentence is not in itself a finding about the gene and the disease. The quoted sentences say what the papers report.
esophageal cancer (2 papers, 2022 to 2025). A primary or metastatic malignant neoplasm involving the esophagus. "Although the consequences of the AP3S1 P158L recurrent mutation in SNSCC are not well understood, recent studies have linked AP3S1 as a driver mutation in esophageal cancer as well as a potential pan-cancer oncogene through facilitation of an immunosuppressive tumor immune microenvironment." (PMID 40500270, 2025).
cervical cancer (1 paper, 2023). A primary or metastatic malignant neoplasm involving the cervix. "Moreover, together with AP3S1, it is downregulated in cervical cancer." (PMID 36979661, 2023).
lung adenocarcinoma (1 paper, 2024). A carcinoma that arises from the lung and is characterized by the presence of malignant glandular epithelial cells. "Previous studies have indicated that AP3S1 promotes tumor cell growth and invasion in lung adenocarcinoma (LUAD) and serves as an oncogene in various cancers; moreover, it is potentially involved in immunosuppressive microenvironments." (PMID 38609993, 2024).
ovarian carcinoma (1 paper, 2024). A malignant neoplasm originating from the surface ovarian epithelium. "The WGCNA results indicated that AP3S1 is associated with lymph node and vascular metastasis in ovarian cancer cells." (PMID 38609993, 2024). "Our analysis of TCGA and other collected data revealed a correlation between AP3S1 expression or mutation and the survival time of ovarian cancer patients." (PMID 38609993, 2024). "We hope to establish more international collaborations, and researchers from multiple research centers can work together to explore and verify the mutation status of AP3S1 in ovarian cancer and its impact on clinical characteristics." (PMID 38609993, 2024). "Our research investigated the correlation of AP3S1 with the ovarian cancer tumor immune response from multiple perspectives, the corroborating prior published studies." (PMID 38609993, 2024). "To further investigate the functional consequences of AP3S1 expression, we used weighted gene coexpression network analysis (WGCNA) to analyze the DEGs associated with AP3S1 in ovarian cancer." (PMID 38609993, 2024). "AP3S1 knockdown experiments in ovarian cancer cells demonstrated its regulatory role in tumor cell migration and invasion through the TGF-β/SMAD pathway." (PMID 38609993, 2024). "The results suggested that AP3S1 expression was most strongly correlated with lymphatic invasion and vascular invasion in ovarian cancer." (PMID 38609993, 2024). "The results showed that the migration ability of ovarian cancer cells was significantly inhibited after AP3S1 knockdown." (PMID 38609993, 2024). "Based on TCGA data, we investigated the relationships between AP3S1 and various immune and stromal cells in the ovarian cancer immune microenvironment." (PMID 38609993, 2024). "We knocked down AP3S1 in ovarian cancer cells and observed a decrease in the protein levels of TGF-β, phosphorylated SMAD2/3 (p-SMAD2/3), vimentin (VIM), and N-cadherin, whereas E-cadherin levels were increased." (PMID 38609993, 2024). "We divided ovarian cancer patients into two groups based on AP3S1 expression levels and calculated the differentially expressed genes (DEGs)." (PMID 38609993, 2024). "Moreover, we validated the results of in vitro experiments and showed that AP3S1 can control the migration and invasion of ovarian cancer cells." (PMID 38609993, 2024). "AP3S1 expression was possibly greater in ovarian cancer tissues than in normal ovarian tissues." (PMID 38609993, 2024). "Additionally, these experiments confirmed that AP3S1 regulates EMT in ovarian cancer cells through the TGF-β/SMAD pathway, thereby promoting tumor cell migration and invasion." (PMID 38609993, 2024). "Immunohistochemistry results from the HPA database suggested that AP3S1 expression may be greater in ovarian cancer tissue than in normal ovarian tissue (Fig-4B)." (PMID 38609993, 2024). "However, more research is still needed to determine the expression and function of AP3S1 in ovarian cancer." (PMID 38609993, 2024). "Moreover, ovarian cancer tumor samples with different AP3S1 expression levels had varying immune checkpoint scores." (PMID 38609993, 2024). "When combining the enrichment analysis results with those of the TGF-β pathway, we hypothesized that AP3S1 may participate in the malignant phenotype of tumors by regulating the migration and invasion abilities of ovarian cancer cells." (PMID 38609993, 2024). "This suggested that AP3S1 could be an oncogene in ovarian cancer." (PMID 38609993, 2024). "Furthermore, knocking down AP3S1 inhibited the proliferation of ovarian cancer cells." (PMID 38609993, 2024). "Our findings suggest that AP3S1 may play a role in ovarian cancer recurrence." (PMID 38609993, 2024). "In vitro experiments also confirmed that AP3S1 can regulate EMT through the TGF-β/SMAD pathway, thereby influencing the migration and invasion capabilities of ovarian cancer cells." (PMID 38609993, 2024).
ovarian carcinoma (continued). "Our findings suggest a correlation between AP3S1 and CD4 + T cells in ovarian cancer, which provides new avenues for further investigating the role of AP3S1 in tumor immunity." (PMID 38609993, 2024). "Transwell experiments were performed after AP3S1 was knocked down in A2780 and SKOV3 cells to explore the regulatory role of AP3S1 in ovarian cancer cell migration." (PMID 38609993, 2024). "However, the TCGA results suggested that low AP3S1 expression had a limited effect on OS and PFS in ovarian cancer patients." (PMID 38609993, 2024). "Due to the fact that no prior studies have explored the correlation of AP3S1 with ovarian cancer, our study focused primarily on investigating its role and mechanisms in ovarian cancer." (PMID 38609993, 2024).
uterine corpus endometrial carcinoma (1 paper, 2022). A endometrial carcinoma (disease) that involves the body of uterus. "Our analysis of AP3S1 gene alterations using cBioPortal showed that the highest alteration frequency of AP3S1 appears for patients in uterine corpus endometrial carcinoma, with “amplification and deep deletion” as the primary types." (PMID 35874816, 2022).
cancer (4 papers, 2014 to 2025). A tumor composed of atypical neoplastic, often pleomorphic cells that invade other tissues. "We observed that the AP3S1 overexpression was positively associated with many malignant pathways in pan-cancer, such as IL6 JAK STAT3 signaling, IL2 STAT5 signaling, TGF BETA signaling, interferon gamma response, and interferon alpha response." (PMID 35874816, 2022). "In addition, we also found that AP3S1 expression was positively correlated with cancer-associated fibroblasts(CAFs) and Tregs." (PMID 35874816, 2022). "We also found that AP3S1 expression was positively correlated with the level of infiltration of immunosuppressive cells (tumor-associated macrophages, cancer-associated fibroblasts, Tregs) and negatively correlated with immune killer cells, including NK cells and CD8+ T cells, in pan-cancer." (PMID 35874816, 2022). "In contrast, in most cancers, AP3S1 expression was negatively correlated with immune killer cells, such as NK cells and CD8+ T cells." (PMID 35874816, 2022). "AP3S1 expression was positively correlated with most immunosuppressive genes in pan-cancer, such as the common CD274 (PD-L1), PDCD1 (PD-1), CTLA4, LAG3, and TIGIT." (PMID 35874816, 2022). "To explore the significance of AP3S1 in cancer immunity, we found that AP3S1 has a broad immunomodulatory function in pan-cancer by using GSEA and GSVA analysis." (PMID 35874816, 2022). "Then, we performed a systematic analysis of the genetic alterations, clinical features, and prognostic value of AP3S1 in pan-cancer." (PMID 35874816, 2022). "In conclusion, our study suggests that AP3S1 is a potential prognostic biomarker and therapeutic target for pan-cancer." (PMID 35874816, 2022). "Our results show that AP3S1 expression positively correlated with the level of infiltration of immunosuppressive cells in pan-cancer, such as TAMs and CAFs." (PMID 35874816, 2022). "AP3S1 expression was positively correlated with most immunosuppressive genes in pan-cancer, such as CD274 (PD-L1), PDCD1 (PD-1), CTLA4, LAG3 and TIGIT." (PMID 35874816, 2022). "To further explore the impact of AP3S1 expression in pan-cancer on patient prognosis, we performed survival analysis of AP3S1 expression and patient survival data using univariate Cox regression analysis (UniCox) and Kaplan-Meier methods." (PMID 35874816, 2022). "In this study, we used multi-omics data from 33 cancers to comprehensively analyse the role of AP3S1, including AP3S1 expression, clinical characteristics, prognostic role, DNA methylation, copy number alteration (CNA), and mutational status." (PMID 35874816, 2022). "In this study, we demonstrated that AP3S1 expression was associated with TMB in four cancer types and MSI in ten cancer types." (PMID 35874816, 2022). "Our study explores the potential pan-cancer role of AP3S1 through an extensive analysis and its function in the tumour microenvironment (TME)." (PMID 35874816, 2022). "Similarly, Kyoto Encyclopedia of Genes and Genomes (KEGG) pathway enrichment analysis, which focuses on identifying significant pathways associated with the DEGs, implicated AP3S1 in oxidative phosphorylation, the TGF-β pathway, and proteoglycans in cancer." (PMID 38609993, 2024). "In addition, gene mutations, DNA methylation, and CNA had important effects on AP3S1 expression in pan-cancer." (PMID 35874816, 2022). "We found that AP3S1 participates in immune regulation-related pathways in pan-cancer, especially for the adaptive and innate immune systems, neutrophil degranulation, HIV infection, cytokine signalling in the immune system, antigen processing and Toll-like receptor cascades." (PMID 35874816, 2022). "Based on this study, researchers could aim to understand the outstanding potential of AP3S1 in tumor immunity, conduct various experiments to explore it in-depth and contribute to cancer treatment." (PMID 35874816, 2022).
cancer (continued). "Therefore, we used three different methods to assess the relevance of AP3S1 levels to immune cell infiltration in pan-cancer." (PMID 35874816, 2022). "The results also showed that AP3S1 expression was closely associated with immune-related pathways, including immune checkpoints, antigen processing mechanisms and CD8 T effectors in pan-cancer." (PMID 35874816, 2022). "We also found that AP3S1 expression significantly and positively correlated with TGFB1 and IL-10 expression in pan-cancer, which in turn were significantly correlated with TAMs/CAFs, and we speculate that this may be a potential mechanism by which AP3S1 affects infiltration of TAMs/CAFs." (PMID 35874816, 2022). "Therefore, we assessed their relationship with AP3S1 expression in pan-cancer." (PMID 35874816, 2022). "The results showed a clear positive correlation between AP3S1 expression and TMB in four cancers, including STAD, LAML, COAD and SKCM." (PMID 35874816, 2022). "In addition, AP3S1 was positively correlated with most immunosuppressive genes, including PD-1, PD-L1, CTLA4, LAG3 and TIGIT in most cancer types." (PMID 35874816, 2022). "In order to elucidate the potential biological pathways that AP3S1 might regulate, we performed a GSEA algorithm analysis using the “clusterprofiler” in pan-cancers and then selected 8 tumors with similar results." (PMID 35874816, 2022). "The expression of AP3S1 could affect TMB and MSI in various cancers." (PMID 35874816, 2022).
tumor (4 papers, 2022 to 2025). "Further analysis of AP3S1 mutations and expression demonstrated their associations with patient survival and the tumor immune response." (PMID 38609993, 2024). "Among the tumor driver genes derived from the mutation data, AP3S1 emerged as the most weighted oncogene." (PMID 38609993, 2024). "GSEA and GSVA results show that AP3S1 is involved in tumor progression and associated with immune pathways in different tumor types." (PMID 35874816, 2022). "GSEA and GSVA results show that AP3S1 is involved in tumor progression and associated with immune pathways in various tumors." (PMID 35874816, 2022). "Finally, we analyzed the association of AP3S1 with tumor mutational burden (TMB), microsatellite instability (MSI), and immune-related genes." (PMID 35874816, 2022). "AP3S1 was identified as being a key player in tumor immunity and prognosis, thus providing new perspectives for personalized treatment strategies." (PMID 38609993, 2024). "The results demonstrated that AP3S1 expression was elevated in the relatively worse tumor stages in ACC, CESC, HNSC, KIRP, LUAD, PAAD, and THCA." (PMID 35874816, 2022). "After analysis of the UALCAN database, AP3S1 protein was upregulated in tumor tissues of HNSC, LIHC, LUAD, and KIRC and downregulated in GBM compared to normal tissues." (PMID 35874816, 2022). "Here, we extensively analyzed the expression profile and prognostic significance of AP3S1 and explored its potential role in tumor immunology." (PMID 35874816, 2022). "A recent study identified AP3S1 as a tumor driver gene after analyzing 1,145 samples from patients with esophageal squamous cell carcinoma." (PMID 35874816, 2022). "In the TCGA dataset, mRNA levels of four genes (CNIH1, KIF20A, GALNT2, and AP3S1) were highly expressed in tumor tissues, while GRIA1 levels were downregulated in tumor tissues." (PMID 36524130, 2022). "Despite these findings, additional studies are needed to reveal more about the role of AP3S1 in tumor development and progression." (PMID 35874816, 2022). "By correlation analysis between AP3S1 and CNA, we found that AP3S1 expression was positively correlated with CNA in most tumor types." (PMID 35874816, 2022). "As for tumor cell lines, we proved that AP3S1 expression was also the highest in MESO cell lines using data from CCLE database." (PMID 35874816, 2022). "In order to compare AP3S1 expression in tumor tissues, our findings revealed that AP3S1 expression was highest in MESO and lowest in KICH." (PMID 35874816, 2022). "The HPA database of protein levels of AP3S1 expression between normal and tumor tissues also confirms similar results." (PMID 35874816, 2022). "Apart from GRIA1, upregulated mRNA levels of CNIH1, KIF20A, GALNT2, and AP3S1 were observed in tumor tissues in these datasets." (PMID 36524130, 2022). "Moreover, we demonstrated the potential role of AP3S1 in tumor immunity and prognosis, which provides new perspectives on targeted therapeutic interventions for this aggressive disease." (PMID 38609993, 2024). "Moreover, we investigated the potential role of AP3S1, which is a candidate gene of interest that was identified from our analysis, in tumor immunity, as well as its prognostic significance in HGSOC." (PMID 38609993, 2024). "Our findings reveal an essential role for AP3S1 in the tumour immunosuppressive microenvironment and AP3S1 could act a potential prognostic and immunotherapeutic biomarker." (PMID 35874816, 2022). "Only a few studies have found a correlation between AP3S1 and tumor progression." (PMID 35874816, 2022). "Targeting AP3S1 could be a novel approach for tumor immunotherapy." (PMID 35874816, 2022). "Additionally, we investigated AP3S1 expression at various tumor stages." (PMID 35874816, 2022). "Tumor driver genes were identified based on the WES data from PUTH samples, and AP3S1 had the highest weight among these genes." (PMID 38609993, 2024).
tumor (continued). "Since GRIA1 was downregulated in LUAD tumor tissues, CNIH1 and AP3S1 were selected for further studies." (PMID 36524130, 2022). "The mRNA levels of CNIH1 and AP3S1 detected in our own LUAD samples were not fit the public data, which may result from that expression of these genes in different tumor stages of LUAD maybe different." (PMID 36524130, 2022).
AP3S1 also shares sentences with these, for which no sentence is quoted: acute myeloid leukemia (1 paper); Glioblastoma multiforme (1); glioma (1); Kidney (1); mesothelioma (1); myeloid neoplasm (1); ovarian serous cystadenocarcinoma (1); Pan (1); Skin Cutaneous Melanoma (1); testicular germ cell tumor (1).